PIK3CA (phosphatidylinositol-4,5-bisphosphate 3-kinase catalytic subunit alpha)
Diseases named in the same sentence as PIK3CA in open-access papers (continued):
Sharing a sentence is not in itself a finding about the gene and the disease.
epilepsy (continued). "BKM120, a 2,6-dimorpholino pyrimidine derivative, is an orally available pan-Class I PI3K inhibitor currently in clinical trials for solid tumors and may represent a novel therapeutic agent for PIK3CA-related epilepsy." (PMID 26633882, 2015). "The discovery that Pik3ca-related epilepsy is independent of dysplasia and susceptible to acute modulation is a major and paradigm shifting finding." (PMID 26633882, 2015). "Interestingly this type of epilepsy does not respond to traditional seizure medications but there is evidence suggesting that targeting the PI3K pathway may reduce the incidence of seizures in PIK3CA driven epilepsy." (PMID 31018529, 2019). "Notably, Pik3ca-associated epilepsy in mice was independent of brain overgrowth and cortical dysplasia." (PMID 26633882, 2015). "Our mouse models faithfully recapitulated the most important PIK3CA-related phenotypes of MEG, hydrocephalus, cortical and white matter dysplasia, and epilepsy." (PMID 26633882, 2015). "Thus Pik3ca-dependent epilepsy is independent of dysmorphology." (PMID 26633882, 2015).
megalencephaly (12 papers, 2015 to 2025). A congenital abnormality in which the occipitofrontal circumference is greater than two standard deviations above the mean for a given age. "In the context of dysregulation of catalytic subunits of PI3K, mutations in PIK3CA gene have been observed in clinical cases of cortical dysplasia and megalencephaly." (PMID 35098253, 2021). "Somatic mutations of PIK3CA, encoding the p110α catalytic subunit of PI3K have been seen generally in tumor cells and segmental overgrowth tissues less frequently, while germline mutations of PIK3CA have been observed in patients with segmental overgrowth or megalencephaly." (PMID 37664840, 2023). "Mice with activating mutations of Pik3ca, the catalytic subunit of the phosphoinositide 3-kinase (PI3K) enzyme, can cause brain overgrowth syndromes comprising megalencephaly, epilepsy, and developmental hydrocephalus." (PMID 39503968, 2025). "Historically, different nomenclatures have been used in this group of patients, including but not limited to macrocephaly-capillary malformation, MCAP, MPPH, hemimegalencephaly, focal cortical dysplasia, megalencephaly, and PIK3CA-related overgrowth spectrum." (PMID 29296277, 2017). "Recently, germline and somatic point mutations in AKT3, PIK3R2, and PIK3CA have been detected in the megalencephaly-related syndrome, and somatic gain of function point mutations in AKT3, PIK3CA, and MTOR has also been detected in HME, the most severe type of megalencephaly." (PMID 28025777, 2017). "Three strongly activating PIK3CA mutations found most commonly in cancer (hotspot mutations) result in severe segmental cortical dysplasia (SEGCD), which includes bilateral dysplastic megalencephaly (MEG), hemimegalencephaly (HMEG) and focal cortical dysplasia (FCD) types 2a/2b." (PMID 26633882, 2015).
astrocytoma (11 papers, 2009 to 2025). "Patients affected by high grade astrocytoma displayed alterations involving PIK3CA (40%), EGFR (40%) and RAS (20%) as previously reported." (PMID 35372034, 2022). "K27M-H3.1 and ACVR1 mutations as well as ALT phenotype were only found in WHO grade III–IV astrocytomas, while PIK3CA mutations and PDGFRA gains/amplifications were found in WHO grade II–IV astrocytomas." (PMID 25047029, 2014). "PIK3CA mutations were present in 14.3 % of DIPGs, including WHO grade II-IV astrocytomas but not PNETs." (PMID 25047029, 2014). "We also identified several mutations not previously reported in pediatric astrocytoma, some of which (EGFR, PIK3CA, PDGFRA) represent potentially actionable targets." (PMID 19924296, 2009).
colon adenocarcinoma (11 papers, 2015 to 2026). "Co-occurrence of PIK3CA mutations with activating mutations in the mitogen activated protein kinase (MAPK) pathway was also observed in 74% of the TCGA colon adenocarcinoma samples." (PMID 26894854, 2016). "In particular, 45 adenocarcinomas (41 colon, 2 lung, 2 pancreas) exhibited co-occurring KRAS and PIK3CA mutations; two colon adenocarcinomas had concomitant BRAF and PIK3CA mutations." (PMID 26435479, 2015). "A set of PIK3CA mutations have been detected and functionally investigated in various cancer types such as BRCA and colon adenocarcinoma (COAD)." (PMID 27356755, 2016).
COVID-19 (11 papers, 2021 to 2024). A disease caused by infection with severe acute respiratory syndrome coronavirus 2. "Dactolisib is a compound targeting PIK3CA that has been tested in a phase II clinical trial for its ability to reduce COVID-19 disease severity (NCT04409327)." (PMID 37137934, 2023). "The underlying mechanisms of kaempferol against COVID-19/PF co-occurrence may be related to bind to EGFR, SRC, MAPK3, MAPK1, MAPK8, AKT1, RELA and PIK3CA." (PMID 35754492, 2022). "The ‘prevalent’ ‘candidate genes’ (ADAM10, ADAM17, AKT1, CTNNB1, ESR1, FGFR1, PIK3CA) might have the most prominent pathophysiological relevance in COVID-19." (PMID 36229517, 2022). "Meanwhile, the correlation analysis of ICD-related DEGs and immune cell infiltration in severe COVID-19 showed that TLR4, PIK3CA, FOXP3, ENTPD1, CD4, CASP1 and BAX were significantly correlated with a variety of immune cell infiltration." (PMID 38600309, 2024). "Jing Fang Bai Du San was found to temporarily improve the clinical symptoms of patients, and network pharmacology analysis initially revealed that the targets of Jing Fang Bai Du San in the treatment of COVID-19 mainly included EGFR, PIK3CA, LCK, and MAPK1." (PMID 36782331, 2023). "According to the results of cytoscape, the targets of JFBDS for treating COVID-19 mainly contained EGFR, PIK3CA, lymphocyte-specific protein tyrosine kinase (LCK), mitogen-activated protein kinase 1 (MAPK1), MAPK3, MAPK8, STAT3, TNF, IL2 and RELA." (PMID 35165507, 2022). "And the key targets of these important pathways, such as AKT1, PIK3CA, PIK3CD and CEP, all have good binding energy, which reveals that CEP treats COVID-19 mainly by acting on these key targets and regulating related pathways." (PMID 35935817, 2022). "In addition, VEGF signaling pathway and HIF-1 signaling pathway are also rich in key targets such as AKT1, PIK3CA and PIK3CD, which may be related to the effect of CEP on COVID-19." (PMID 35935817, 2022).
neuroblastoma (11 papers, 2006 to 2025). Neuroblastoma (NB) is the most common solid, extracranial childhood tumor. "Pik3ca, Ras family, and Braf activating mutations occur rarely in human neuroblastomas or in a murine model driven by neural-restricted MYCN overexpression." (PMID 16822308, 2006). "Sixty-nine human neuroblastomas (42 primary tumors and 27 cell lines) were sequenced for PIK3CA activating mutations within the C2, helical and kinase domain "hot spots" where 80% of mutations cluster." (PMID 16822308, 2006). "We therefore assessed PIK3CA for mutation in human neuroblastomas, as well as in neuroblastomas arising in transgenic mice with MYCN overexpressed in neural-crest tissues." (PMID 16822308, 2006). "Mutations in the PIK3CA gene were also observed in human neuroblastoma tissues." (PMID 41142119, 2025). "We identified mutations in the PIK3CA gene in 2 of 69 human neuroblastomas (2.9%)." (PMID 16822308, 2006). "The third sample, the zPDX from the neuroblastoma culture with MYCN amplification and PIK3CA (phosphatidylinositol-4,5-bisphosphate 3-kinase catalytic subunit alpha) mutation, responded only moderately to the ALK inhibitor ceritinib out of five tested drugs." (PMID 35159116, 2022). "PIK3CA, indeed, was expressed at higher levels in neuroblastoma tissues than in normal tissues, including the adrenal gland." (PMID 36585695, 2022). "The enhanced sensitivity of MYCN overexpressing neuroblastoma cell lines to PI3K/mTOR inhibition is somewhat surprising, since these cells lack intrinsic mutations in the PI3K pathway members PTEN or PIK3CA." (PMID 27438153, 2016). "Mutations in PIK3CA and PTEN are frequently reported in other malignancies but are rarely seen in neuroblastoma." (PMID 23597230, 2013). "In contrast, gain of 3q26 including the PIK3CA locus is infrequently reported in neuroblastoma cells, including in those cell lines studied herein." (PMID 16822308, 2006). "We found that expression of ALK and PIK3CA were positively correlated in neuroblastoma samples." (PMID 36585695, 2022). "Therefore, we performed a targeted sequencing analysis of the PIK3CA gene in primary neuroblastomas and neuroblastoma-derived cell lines." (PMID 16822308, 2006). "Additionally, Ras family members (Hras1, Kras2 and Nras) and the downstream effectors Pik3ca and Braf, were sequenced from twenty-five neuroblastomas arising in neuroblastoma-prone transgenic mice." (PMID 16822308, 2006). "In the International Neuroblastoma Staging System (INSS)-stage stratified neuroblastoma samples, we found that higher PIK3CA expression was highly correlated to the more advanced stages." (PMID 36585695, 2022). "In neuroblastomas, abnormal receptor tyrosine kinase (RTK) activity (e.g., ALK, NTRK) occurs frequently, but the frequency of genetic aberrations of downstream effectors, such as PIK3CA is rather low." (PMID 35159116, 2022). "PLK-1, CDK-1, PIK3CA, ATF4, TEAD4 and ALYREF could enhance MYCN protein stability and sustain MYCN expression in neuroblastoma." (PMID 35820898, 2022). "Oncogenic mutations of PIK3CA, encoding p110α, are common in various malignancies but rare in neuroblastoma tumors, and there has been no reports of a difference in PIK3CA-mRNA expression between different stages of neuroblastoma." (PMID 23597230, 2013).
uterine serous carcinoma (11 papers, 2014 to 2025). "In uterine serous carcinoma with PIK3CA mutations and overexpress HER2/neu, taselisib has demonstrated high activity in reducing tumour growth in vivo." (PMID 40292733, 2025). "First, we measured the response of TCR4-transduced T cells to a patient-derived xenograft (PDX) generated from an HLA-A*03:01+ patient with Mut PIK3CA uterine serous carcinoma (PDX USC_X10)." (PMID 35484264, 2022). "In mouse models of uterine serous carcinoma, combined ridaforolimus and HER2 blockade with lapatinib/trastuzumab had a better anti-tumor activity when tumors had PIK3CA (E542K) mutations together with HER2 gene amplification rather than those without PIK3CA mutations." (PMID 31817676, 2019).
biliary tract cancer (10 papers, 2015 to 2025). "While more frequently seen in gallbladder carcinoma, PIK3CA mutations also occur in subsets of biliary tract cancers, indicating shared oncogenic pathways across these malignancies." (PMID 41300430, 2025). "A whole-exome and transcriptome sequencing study of biliary tract cancer showed that a subgroup with an enrichment of hypermutations such as PIK3CA, which encodes PI3K, correlated with expression of immune checkpoint molecules, including PD-L1." (PMID 29732001, 2018). "PIK3CA mutation is considered a good candidate for targeted therapies in cancers, especially biliary tract cancer (BTC)." (PMID 26498688, 2015). "In a cohort of 34 patients with biliary tract cancer, actionable variants were detected in IDH1/2 (18%), followed by FGFR1/2 (16%), EGFR or ERBB2/3 (16%), PTEN (14%), MDM2 (10%), and PIK3CA (10%)." (PMID 36290850, 2022). "Driver genes, such as the ERBB2, PIK3CA, IDH1/2, BRCA1/2, and FGFR2 fusion genes, have been identified in gallbladder and biliary tract cancers." (PMID 34573929, 2021). "For example, PTEN, MDM2, and PIK3CA are not considered to be druggable markers for patients with biliary tract cancer under the latest knowledge." (PMID 36290850, 2022).
capillary malformation (10 papers, 2017 to 2024). "Cases of undergrowth associated with lymphatic, venous or venous-capillary malformations, accompanied by variants in the PIK3CA gene, have been identified, highlighting this less-explored aspect alongside overgrowth in such conditions." (PMID 38136956, 2023). "Six of nine patients with capillary malformation and overgrowth (CMO) carried the recurrent GNAQ somatic mutation p.Arg183Gln, while two had PIK3CA mutations." (PMID 35740480, 2022).
ductal carcinomas (10 papers, 2016 to 2025). "PIK3CA also showed a preference for p85-binding domain mutations in uterine adenocarcinoma compared to other cancer types, such as breast ductal carcinoma, which are enriched for mutations in the PIK family domain." (PMID 38890488, 2024). "Across nine studies that reported tumor histology by PIK3CA mutation status, most were also from ductal carcinomas (range: 63.2% to 99%)." (PMID 32637176, 2020). "In accordance with PIK3CA mutations developing in a hormone receptor rich environment, these mutations were more frequently observed in lobular than in ductal carcinomas, a finding that has been reported by others, as well." (PMID 27129168, 2016). "While the association between mast cell gene expression and CDH1 mutation was as expected linked to lobular breast cancer, PIK3CA and MAP3K1 mutations were selectively associated with mast cell gene expression when considering only ductal carcinoma." (PMID 30993001, 2019).
hemimegalencephaly (10 papers, 2015 to 2025). "In the brain, the phenotypic spectrum of PIK3CA-related segmental overgrowth includes bilateral dysplastic megalencephaly, hemimegalencephaly and focal cortical dysplasia, the most common cause of intractable pediatric epilepsy." (PMID 26633882, 2015). "Here, we report the first paediatric case series of the use of miransertib in two children with severe PIK3CA-related overgrowth spectrum, one with CLOVES variant and one with facial infiltrating lipomatosis with hemimegalencephaly." (PMID 33639990, 2021). "PIK3CA-related segmental overgrowth also occurs within the brain, resulting in bilateral dysplastic megalencephaly, hemimegalencephaly and focal cortical dysplasia." (PMID 31018529, 2019). "Using exome sequencing, recent studies have identified de novo germline and somatic mutations of PI3K-AKT-mTOR components (PIK3CA, AKT3, and MTOR genes) in patients with hemimegalencephaly." (PMID 26541977, 2015). "Hemimegalencephaly, a condition in which one side of the brain is larger than the other, is also attributed to an activating PIK3CA E545K that is indistinguishable from the alteration observed in several types of malignant neoplasms, but there is no clear cancer risk in hemimegalencephaly." (PMID 32066498, 2020).
invasive carcinoma (10 papers, 2012 to 2025). A carcinoma that is not confined to the epithelium, and has spread to the surrounding stroma. "However, as these lesions progress to concurrent DCIS or invasive carcinoma, malignant clones often lack PIK3CA driver mutations, instead displaying complex copy number alterations across multiple chromosomal regions." (PMID 41244906, 2025). "In addition, cytogenetic analyses demonstrated that 3q26 amplification is an early event in HNSCC tumorigenesis, and PIK3CA amplification and expression has been detected in dysplasias and associated with progression to invasive carcinoma." (PMID 30823625, 2019). "Nonetheless, PIK3CA gene amplification showed a more prominent role, since it was detected in over 50% of laryngeal dysplasias, and 70% of the lesions that progressed to invasive carcinoma." (PMID 38473941, 2024). "On the other hand, it is known that, unlike non-special luminal invasive carcinomas, NEBCs have a significantly lower frequency of PIK3CA mutations." (PMID 32414120, 2020). "In human cancer, PIK3CA mutations are detected in DCIS suggesting that PIK3CA mutation is an early event in the tumorigenic process and that, presumably, other mutational events are required to initiate progression to invasive carcinoma." (PMID 22666336, 2012). "Upregulation of Phosphatidylinositol-4,5-Bisphosphate 3-Kinase Catalytic Subunit Alpha (PIK3CA) has been elicited in a minority of CIN 3 and a high proportion of invasive carcinomas." (PMID 34250016, 2021).
invasive lobular carcinoma (10 papers, 2015 to 2025). "CDH1 germline mutations have been associated with hereditary lobular breast cancer and hereditary diffuse gastric cancer, while a recent study linked mutations in CDH1 and PIK3CA to the immune-related invasive lobular carcinoma of the breast." (PMID 32471470, 2020). "In concordance with these findings, a recent analysis of invasive lobular adenocarcinomas has demonstrated that PI3K/AKT signalling is more highly elevated in PTEN-deficient tumors than in PIK3CA mutants." (PMID 26814435, 2016). "The aim of the study was to evaluate the independent prognostic role of PIK3CA activating mutations and an association between PIK3CA activating mutations and efficacy of adjuvant endocrine therapy (ET) in patients with operable invasive lobular carcinoma (ILC)." (PMID 37341201, 2023).